EGFR (epidermal growth factor receptor)
Diseases named in the same sentence as EGFR in open-access papers (continued):
Sharing a sentence is not in itself a finding about the gene and the disease.
cancer (continued). "To investigate if combination therapy targeting EGFR and BCL6 would be more effective in killing cancer cells than monotherapy we treated all three cell lines with gefitinib and FX1, alone or in combination, and evaluated survival using clonogenic assay." (PMID 32234966, 2020). "VEGF is the central component of pathological blood vessel formation, and it was reported that EGFR and ERBB2 signaling pathway plays an essential role in VEGF regulation in carcinoma cells." (PMID 32224504, 2020). "Peptides based on interaction motifs in syndecan-1 and syndecan-4, named synstatins or SSTN peptides, are potential therapeutic agents for carcinomas depending on the HER2 and epidermal growth factor receptor (EGFR) pathway for their invasion and survival." (PMID 32351878, 2020). "In fact, inhibition of receptor tyrosine kinases including the epidermal growth factor receptor (EGFR) and HER2 in experimental cancer models can trigger feedback activation of STAT3 as a possible mechanism of resistance to targeted therapies." (PMID 31297057, 2019). "However, one of the issues with EGFR inhibitors is their extensive side effect profile which may be drug and/or receptor specific, as well as a potential for drug resistance, as is typical in cancer patients receiving EGFR inhibitors." (PMID 31675376, 2019). "Excessive growth/proliferation is one of the ‘hallmarks of cancer’, and these growth signals are often mediated by receptors on the cell surface such as HER2 and EGFR." (PMID 30959799, 2019). "As previously stated, the autophosphorylation of the tyrosine residues on EGFR results in the activation of the Ras/Raf/MAPK/ERK pathway, which modulates cell growth and proliferation, and is commonly hyperactive in cancers." (PMID 31200451, 2019). "Soluble factor Amphiregulin binds EGFR and acts as an autocrine growth factor for establishing a positive autocrine regulatory feedback loop between EGFR and YAP1, which is important in cancer progression." (PMID 30805310, 2019). "In particular, a Src-mediated crosstalk between AHR and EGFR has been shown to trigger the activation of ERK1/2 and the stimulation of proliferative effects in cancer cells." (PMID 31370872, 2019). "Hierarchical cluster analysis of the growth inhibition rate showed that cancer cells in the same genotype tended to present similar metabolic vulnerabilities, especially for FGFR- and EGFR-aberrant cells that showed a trend of clustering." (PMID 31221965, 2019). "In summary, we demonstrated that TGIF2 was highly expressed in LUAD and upregulated OCT4 expression downstream of EGFR/RAS/ERK signaling, promoting cancer cell stemness and metastasis of LUAD cells." (PMID 31871777, 2019). "Lessons learned from studying molecular mechanisms of resistance to ABL, EGFR, ALK, KIT, and RAF inhibitors in human cancers have highlighted the need for next-generation kinase inhibitors that are effective against acquired secondary resistance mutations." (PMID 31371345, 2019). "The EGFR‐overexpressing cancer cells were the KYSE520, A431, MDA‐MB‐468, AsPC‐1, and HCC827 cells, the EGFR relative low‐expressing cells were the A549, KYSE150, MCF‐7, and NCI‐H1975 cells, and the EGFR‐lacking expression cells were the Karpas 299 cells." (PMID 30372581, 2019). "In recent years, the discovery of multiple pathways leading to the escape from anti-EGFR therapy has revealed an enormous complexity and heterogeneity of human CRC due to the intrinsic genomic instability and immune/cancer cell interaction." (PMID 31370270, 2019). "B) Normal and OPSCC cancer tissues are stained with DAPI, Pancytokeratin (PCK) and EGFR, shown as merged image in right most column (DAPI=blue, PCK=green, EGFR=red)." (PMID 30630536, 2019). "In a panel of cell lines, CAR-EXO-CTX and CAR-EXO-TTZ show notable cytotoxic effects on EGFR-expressing cells or HER2-expressing cells, while cancer cells with low antigen expression seemed to be resistant to exosome-mediated lysis." (PMID 31554797, 2019).
cancer (continued). "Many studies have shown that the EGFR/MAPK pathway is aberrantly activated in CRC46, which is thought to be responsible for cancer cell proliferation and metastasis." (PMID 31853225, 2019). "Activating oncogenic mutations generally occur at specific residues with a high frequency across cancers, examples include the G12 residue in KRAS, the V600 residue in BRAF, and the L858 residue in epidermal growth factor receptor (EGFR)." (PMID 30548122, 2019). "Targeting the receptors upstream of Ras isoforms, such as EGFR, as well as its downstream effectors, such as BRAF, however, has proven to be a successful strategy to achieve positive clinical impacts in human cancer." (PMID 31712554, 2019). "Several important targets (EGFR and MAPK1) and pathways (pathways in cancer and MAPK signaling pathway) were predicted to be an important role in the mechanism of QRLDD." (PMID 30719056, 2019). "First of all, nanobodies targeting cancer-specific membrane proteins (e.g. HER2, EGFR, M-protein, CD20 and CD38) have been evaluated for both imaging and therapeutic applications 73,95,96,122,130,144,147,211." (PMID 31695800, 2019). "We previously demonstrated that EGFR induces HER3 overexpression to promote the formation and survival of HCC827- and A549-derived cancer stem-like tumorspheres." (PMID 31619200, 2019). "We have previously demonstrated that NRP-1 acts as a multiple co-receptor to promote the proliferation of cancer cells by activating the VEGF/VEGFR2 (VEGF receptor 2), EGF/EGFR (EGF receptor) and HGF/c-Met pathways." (PMID 31572065, 2019). "In this study, we analyzed Lapatinib sensitivity to EGFR and ERBB2 targeted therapy pan-cancer cell line wide." (PMID 30842786, 2019). "Acting together, they not only catalyse the cell proliferation process, but also transactivate the epidermal growth factor receptor (EGFR), which enhances the migration and invasion power of the cancer malignancy." (PMID 31234411, 2019). "The value of EGFR-CAR T cells in treating solid cancers has been demonstrated in both preclinical and clinical settings in a few different cancer types but its potential in treating PDAC is yet to be tested." (PMID 30809507, 2019). "Using Western Blot, we also noticed increased levels of EGFR, MET, and selected markers of cancer stem cells in generated cell lines." (PMID 31877948, 2019). "For example, epidermal growth factor receptor (EGFR, responsible for epithelial tissue development and homeostasis) is overexpressed in cancerous cells relative to normal cells, as cancer cells grow and divide vigorously." (PMID 31304563, 2019). "Dual inhibition of EGFR and MET has previously been demonstrated to suppress invasion of cancer cells." (PMID 31506424, 2019). "The EGFR/FAK/Src pathway is crucial for signaling angiogenesis, cell survival, and anoikis resistance in various types of cancer cells." (PMID 31416203, 2019). "Since functional cross-talk of MET was described in various cancers with other RTKs, we also analyzed the eventual cross-talk of MET with EGFR which is known to be significantly expressed in the TTA1 cell line." (PMID 31040922, 2019). "EGFR is a member of the ErbB/HER (human epidermal growth factor) kinases family, and is involved in cancer cell proliferation, survival, and growth." (PMID 31554160, 2019). "ERBB2 and ERBB3 genes belong to the epidermal growth factor receptor (EGFR) family, and they had been identified as common driver genes of multiple cancer types by promoting solid tumor growth." (PMID 32038722, 2019). "Dysregulation of EGFR and the HER receptor family has been shown to be a key process in tumourigenesis and the progression of cancer." (PMID 31588230, 2019). "Indeed, known EGFR inhibitors that preferentially recognize the active kinase conformation, as promoted by the ΔELREA deletion, exert a more dramatic effect–reducing cell survival in cancer cell models–in comparison to conformationally malleable wild-type EGFR." (PMID 31536605, 2019).
cancer (continued). "Among the signal transduction pathways involved in adaptive cancer response to therapy are tyrosine kinase receptors (RTKs) regulated by NRP1, such as EGFR and IGF1-R, and intracellular effectors, such as PI3K/AKT, MAPK/ERK or NF-κB." (PMID 31027288, 2019). "This more aggressive nature of highly EGFR expressing tumors is consistent with other reports in HNSCC and other cancer types." (PMID 31998639, 2019). "A mechanism study indicated that the increased HSP90 expression along with its client proteins, EGFR, IGF-1R, and Src, promotes autophagy in cancer cells and confers drug resistance." (PMID 31878360, 2019). "A study had identified a crosstalk between AR and epidermal growth factor receptor (EGFR), which is involved in cancer cell growth, in ER-positive BC cells." (PMID 31151151, 2019). "In this study, we found that EGFR TKIs, including gefitinib and AZD9291, impaired lysosome-dependent degradation of SQSTM1, thus compromising their anti-cancer efficiency." (PMID 31637005, 2019). "EGFR and its downstream PI3K pathway are commonly deregulated in many cancers, including breast and head and neck cancer (HNC), making them promising therapeutic targets." (PMID 31235839, 2019). "EGFR inhibition significantly reduced CD47 expression on the surface of pre-apoptotic cells, favoring more efficient engulfment of cancer cells by monocyte-derived dendritic cells." (PMID 32082304, 2019). "Accumulated evidence has demonstrated that SCD1 promotes the activation of EGFR/PI3K/AKT signaling for cell survival, proliferation and chemotherapy resistance in many cancer types." (PMID 31019378, 2019). "Several members of this receptor family (HER2, EGFR, VEGFR, etc.)have become important targets for clinical anti‐cancer therapies, including small molecular inhibitors and antibody‐based therapies." (PMID 31116512, 2019). "It has been reported that EGFR activation can be regulated by the Src and/or AKT signaling in different types of cancer cells." (PMID 31805962, 2019). "Epidermal growth factor receptor (EGFR) and its downstream phosphoinositide 3-kinase (PI3K) pathway are commonly deregulated in cancer." (PMID 31235839, 2019). "Tyrosine kinase receptors (RTK), such as epidermal growth factor receptor (EGFR) and fibroblast growth factor receptor (FGFR), are well recognized oncogenic drivers for the malignant growth of various types of human cancer." (PMID 31221965, 2019). "The EGFR/MAPK pathway is aberrantly activated in CRC, which is thought to be responsible for cancer cell proliferation, migration, and invasion." (PMID 31853225, 2019). "Vandetanib is a small molecule TKI that targets key signaling pathways in cancer by inhibiting VEGFR-dependent tumour angiogenesis and EGFR- and RET-dependent cell proliferation and survival, and is used to treat tumours of the thyroid gland." (PMID 35582714, 2019). "We also compared the genes identified for LUAD and LUSC and found only five genes (ARID1A, CDKN2A, EGFR, MLL3, and RB1) are common for the two cancer types, demonstrating their different disease mechanism." (PMID 30828525, 2019). "In particular, it has been demonstrated that certain AHR ligands stimulate rapid kinase activation, gene expression changes and growth effects in cancer cells through a cross-talk between AHR and EGFR/ERK-mediated signaling." (PMID 31370872, 2019). "In the present study, we identified a novel link between MICAL‐L2 and EGFR, providing a basis for further exploring the role of EGF/EGFR signalling in MICAL‐L2‐facilitated cancer cell migration." (PMID 31034158, 2019). "DDAs and TRAIL synergize to kill cancer cells and are cytotoxic to HER2+ cancer cells with acquired resistance to the EGFR/HER2 tyrosine kinase inhibitor Lapatinib." (PMID 31839995, 2019).
cancer (continued). "The association between EGFR mutation status and BM in NSCLC patients has previously been investigated, although no clear conclusions could be drawn from those investigations, with the molecular aspects of the pathway by which EGFR-mutated cancer cells metastasize remaining unclear to date." (PMID 31048854, 2019). "The human epidermal growth factor receptor (HER) family of transmembrane tyrosine kinases is overexpressed and correlates with poor prognosis and decreased survival in many cancers." (PMID 31215437, 2019). "A simple and robust assay is adopted to evaluate the light‐mediated binding of 7D12 mutants to its target, epidermal growth factor receptor (EGFR), on the surface of cancer cells." (PMID 31609054, 2019). "To further enhance the anti-cancer effects and avoid the side effects, we developed the MPEG-PLA nanoparticles to co-encapsulate Cilen and EGFR inhibitors." (PMID 31316001, 2019). "Taken together, these data indicate that the combination of targeting either EGFR or MUC1 and paclitaxel blocks paclitaxel-resistant CSCs, and thereby prevents recurrence of MUC1-positive cancer." (PMID 31772161, 2019). "Functional cross-talk of MET with other RTKs, such as EGFR, HER2, HER3, RET or IGF1R, was identified in various cancers as mediating inhibitors resistance." (PMID 31040922, 2019). "Epidermal growth factor receptor (EGFR) plays critical roles in cell proliferation, tumorigenesis, and anti-cancer drug resistance." (PMID 31527477, 2019). "Examples of RTKs that frequently have alterations in cancer cells, and therefore are constitutively providing oncogenic signals, are VEGFR, EGFR, HER2 and c-MET (hepatocyte growth factor receptor)." (PMID 31695800, 2019). "In cancer, HER3 can stimulate the oncogenic activity of epidermal growth factor receptor (EGFR) and human epidermal growth factor receptor 2 (HER2) and the resistance to HER-targeted cancer therapies." (PMID 30679757, 2019). "The CSmiR-Tar database identified erythroblastic oncogene B 2 (ERBB2) as a potential target gene of miR-301, across all cancer stages, with a binding site in the 5'UTR of ERBB2 which is structurally related to EGFR." (PMID 31756185, 2019). "Overexpression of epidermal growth factor receptor (EGFR) plays a role in NSCLC, making anti-EGFR drugs an attractive therapeutic option for this cancer." (PMID 31651282, 2019). "We assessed EGFR mRNA expression and its correlation with overall survival (OS), TNM stage and grade of patients from 30 datasets covering 15 cancer types and compared 30 studies in this regard." (PMID 30956774, 2019). "NRP2 also regulates the number of EGFR on the surface of cancer cells, thereby controlling EGF-mediated signaling and response to EGFR-targeted therapy." (PMID 30717262, 2019). "Lapatinib, an EGFR and ERBB2 receptor inhibitor, is used in theclinics, e.g. in combination therapies to treat cancers." (PMID 30623207, 2019). "Previously, we demonstrated that EGFR induces HER3 overexpression, which facilitates the formation of cancer stem-like tumorspheres." (PMID 31619200, 2019). "Inhibiting EGFR and HER2 with receptor-targeted TKIs is an important therapeutic approach in these cancers." (PMID 30671765, 2019). "EGFR-SRC signaling-stimulated NADPH oxidase NOX4 enhances anoikis (cell detachment-induced apoptosis) resistance and survival of cancer cells, which are detached from the ECM but are still anchorage dependent and thereby sensitive to anoikis." (PMID 29478325, 2019).
cancer (continued). "We identified 156 focal amplifications and 69 focal deletions, in well-known oncogenes, such as ERBB2, CCNE1, KRAS, MYC, EGFR, and CDK6, and cancer-related genes such as GATA4, GATA6, CD44 and ZNF217." (PMID 31570735, 2019). "TEADs are mediators of the EGFR-RAS-RAF-MAPK pathway, which is one of the most deregulated molecular pathways in human cancers." (PMID 31212916, 2019). "As key intermediates in oncogenic EGFR, MAPK, RAS/RAF/MEK/ERK and PI3K/AKT/mTOR signaling, FAM83 involved in a variety of important cancer cell signaling functions and overexpressed in many human cancers." (PMID 30910840, 2019). "For example, EGFR signaling promotes not only glycolysis, but also de novo fatty acid synthesis via the PI3K/Akt signaling pathway in cancer cells." (PMID 30735525, 2019). "Activation of EGFR, in turn, activates its downstream kinases, such as Akt and ERK, thereby promoting the proliferation and invasion of cancer cells." (PMID 30759826, 2019). "Thus, our findings have not only revealed previously unknown significance of EGF-stimulated release of SHCBP1 but more importantly also uncovered a new mode of crosstalk between the EGFR and β-catenin pathways and a novel mechanism involved in EGFR regulation of cancer cell stemness." (PMID 30177836, 2019). "There were several established cancer genes involved in a total of 12 common CNAs identified according to GISTIC, including EGFR, CCND1, FHIT, and FAT1." (PMID 31159251, 2019). "ANE can activate EGFR, and inhibition of EGFR and JAK signaling by PD153035 and AG490 also suppressed the ANE-induced MMP-9 production of SAS cancer cells." (PMID 31831717, 2019). "EGFR can activate the RAS‐MEK‐ERK pathway and lead to cell proliferation and survival, which makes it a suitable target for cancer inhibition." (PMID 31368612, 2019). "YAP is involved in resistance to a variety of chemotherapeutic drugs in several cancer types, including molecular targeted drugs such as inhibitors of CDK4/6, EGFR and BRAF, as well as classical cytotoxic drugs such as 5-FU, cisplatin (CDDP) and doxorubicin." (PMID 31540262, 2019). "Initially, to screen the expression levels of EGFR and EPS8 in cancer and normal cell lines, we performed a western blot analysis." (PMID 31118055, 2019). "This identified ATF4, FOXO1, HIF1A, MAF, MYC, and SREBP1 in FGFR-dependent cancer cells whereas ATF4 and MYC in EGFR-addicted cancer cells, which were required for the transcription of the signature genes in glycolysis or SSP." (PMID 31221965, 2019). "The pathway analysis revealed that these lncRNAs participated in several cancer-related signaling pathways including apoptosis, the PI3K-AKT signaling pathway, and the EGFR signaling pathway." (PMID 30984308, 2019). "Compared to monolayer condition, cancer stem cell marker CD24 and EGFR decreased in vivo from 70% to 35% and 100% to 25%, respectively." (PMID 31527554, 2019). "For example, MAPK/ERK signaling inhibited EGFR/PI3`K/AKT-mediated tissue factor (an initiator of blood coagulation and a participant in cancer progression and metastasis) expression in MDA-MB-231 cells." (PMID 31014367, 2019). "Overexpression of EGFR antagonizes neoalbaconol‐induced VEGF reduction and impairs anti‐angiogenesis of neoalbaconol in cancer." (PMID 31368612, 2019). "Trastuzumab was the first anti-cancer monoclonal antibody developed (for the HER2/neu receptor, a close relative of EGFR), while lapatinib is a small-molecule inhibitor of both the HER2/neu receptor and EGFR." (PMID 31366129, 2019). "This method has been used to detect two cancer mutants, BRAF V600E and EGFR L858R, and appears to be a highly sensitive detection approach." (PMID 30911676, 2019). "miR-302a restored CTX responsiveness by directly suppressing CD44, which induced cancer stem cell (CSC)-like properties and activated EGFR-dependent MAPK and AKT signaling." (PMID 31754405, 2019).